ANGPTL4 (angiopoietin like 4)
Diseases named in the same sentence as ANGPTL4 in open-access papers (continued):
Sharing a sentence is not in itself a finding about the gene and the disease.
tumor (continued). "Moreover, GP1 displayed increased expression of angiogenic features (e.g., ANGPTL4, EGFR, AAMP) and complement and coagulation cascade components (e.g., C1, C7, C8, C9, PLG, SERPINE1), which have been associated with aggravated tumor invasion." (PMID 35440542, 2022). "ANGPTL4 plays an important role in the tumour microenvironment, especially in hypoxia induction." (PMID 35285130, 2022). "Given that overexpression of ANGPTL4 reduced the progression of OS, increasing the expression of ANGPTL4 in tumor cells of patients with OS may be a promising therapeutic strategy for OS in the future." (PMID 35461343, 2022). "However, some subsequent studies demonstrated that ANGPTL4 showed an antiangiogenic effect as well as antitumor cell invasion and migration effects during tumor progression." (PMID 35461343, 2022). "However, how ANGPTL4 participates in tumour cell energy metabolism, especially its mechanism in NSCLC, remains to be elucidated." (PMID 35285130, 2022). "Apart from influencing tumour progression, ANGPTL4 could also serve as predictor of cancer development." (PMID 36050447, 2022). "Whether ω‐PUFAs participate in tumour energy metabolism and inhibit tumour cell proliferation through ANGPTL4 remains to be further clarified." (PMID 35285130, 2022). "HIF-1α could directly upregulate ANGPTL4 and promoted tumour metastasis by activating the vascular cell adhesion molecule-1/integrin β1 signalling axis." (PMID 36050447, 2022). "Together, the inhibition of ANGPTL4 expression can inhibit tumor growth and proliferation." (PMID 36467503, 2022). "In comparison, ANGPTL4 was lower expressed in tumor tissues." (PMID 35692877, 2022). "Indeed, the injection of ANGPTL4-overexpressing adenoviral vectors via the portal vein in mice bearing orthotopic liver cancer xenografts resulted in the suppression of both tumor growth and metastasis formation." (PMID 36074318, 2022). "Additionally, 14 prognosis-related genes in LUAD, including one hypoxia-related gene, ANGPTL4, were significantly expressed in the tumor tissues." (PMID 36245988, 2022). "ANGPTL4 exhibits structural similarity to multifunctional angiopoietins, which are involved in glucose homeostasis, lipid metabolism, angiogenesis, inflammation, and tumour progression and metastasis." (PMID 35285130, 2022). "Previous studies reported that ANGPTL4 disrupt the endothelial cell-cell junction and enhance the tumor cells infiltration into adjacent capillary which may begin distant metastasis to other organs through blood flow." (PMID 35392474, 2022). "Moreover, emerging evidence indicates that ANGPTL4 expression, induced by hypoxia-inducible factor 1 alpha (HIF1α) under hypoxic conditions, promotes tumor cells aggressiveness and metastasis." (PMID 35392474, 2022). "EMT is essential for tumor metastasis and invasion 20 and given our results showing ANGPTL4 could regulate the migration and invasion of CRC cells, we asked whether ANGPTL4 was involved in the EMT process of CRC cells." (PMID 34405010, 2021). "ANGPTL4 is an angiopoietin-like protein 4 expressed by tumor and endothelial cells." (PMID 34046336, 2021). "This is connected with induction of murine T regulatory lymphocytes and M2 macrophages, which could be one of the mechanisms of tumor promotion mediated by ANGPTL4." (PMID 34445141, 2021). "Furthermore, TGF-β was found to prime tumor cells for pulmonary metastasis through initiation of angiopoietin-like 4 (ANGPTL4) via SMAD pathway in BC microenvironment." (PMID 34326372, 2021). "In order to further detect whether ANGPTL4 is highly expressed in GCAFs in vivo, tumor xenograft model was established by injecting cells co‐cultured of GBC‐SD and GCAFs/NFs." (PMID 34331381, 2021). "Furthermore, total VE-cadherin levels in ANGPTL4 knockdown tumor lysates were decreased compared to those in the corresponding Ctl tumors." (PMID 33726754, 2021).
tumor (continued). "To assess whether silencing ANGPTL4 affected the promotion of cancer metastasis by activating fibroblast signaling in the tumor microenvironment, we constructed nude mice models." (PMID 34405010, 2021). "Combining these results with the capability of ANGPTL4 to modulate the function of AKT/PKB in conferring anoikis resistance on tumor cells, it remains to be confirmed whether ANGPTL4 also alters cancer cell metabolism." (PMID 33726754, 2021). "Moreover, ANGPTL4 is a secreted protein that can be detected in the serum, and ANGPTL4 expression in various tumor tissues correlates with patients’ poor prognosis." (PMID 34331381, 2021). "Members of the ANGPTL protein family have been proposed as LILR ligands, and ANGPTL4 may act as a tumor suppressor or promoter of cancer metastasis, depending on the cell type and stage of cancer." (PMID 33918618, 2021). "In this study, we aimed to analyze clinical samples of CRC for the expression level of ANGPTL4 gene in the tumor tissue of CRC patients, detect the DNA methylation level of ANGPTL4 promoter in CRC cell lines, and to further study cancer-related fibroblasts during TME changes." (PMID 34405010, 2021). "These different phenotypes could be explained by a differential biological effect of ANGPTL4 fragments on tumor cell proliferation and invasiveness." (PMID 32405335, 2020). "Additionally, to evaluate the effect of NiCl2 on normal and tumour cells, the expression of ANGPTL4 mRNA, and protein was investigated in various normal and tumour lung cell lines that were cultured under the treatment of NiCl2." (PMID 31963541, 2020). "Moreover, a reduction in cancer progression was observed when ANGPTL4 was maintained in the tumor cells but reduced in the microenvironment." (PMID 32928141, 2020). "ANGPTL4 fibrinogen-like domain interacts with and activates specific integrins to facilitate wound healing, modulation of vascular permeability, regulation of ROS levels, tumor growth, angiogenesis and invasion/metastasis." (PMID 32867190, 2020). "These hypotheses suggest that the expression level and effects of ANGPTL4 in cancer may be context- and tumor-type-dependent, which may explain the diversity of previous studies." (PMID 32928141, 2020). "Another study found that circulating ANGPTL4 in the tumor microenvironment might be excreted by other cell types, such as adipocytes, which could accelerate cell proliferation and metastasis." (PMID 32928141, 2020). "Nevertheless, these evidences implied ANGPTL4 is potential target in tumor therapy." (PMID 33196458, 2020). "However, it seemed that ANGPTL4 acted in a tumor type‐dependent manner and even the findings in the same type of cancer contradicted with each other sometimes, too." (PMID 32410376, 2020). "This contradictory ability of ANGPTL4 in cancer progression might be dependent upon context, tumour type, or tissue/cell-specific post-translational modifications." (PMID 31963541, 2020). "Angiopoietin-like protein 4 (ANGPTL4) exhibits structural similarity to the multifunctional angiopoietins, which are involved in glucose homeostasis, lipid metabolism, angiogenesis, inflammation, and tumour progression and metastasis." (PMID 31963541, 2020). "Tumor-derived ANGPTL4 conferred anoikis resistance of tumor cells via autocrine adhesion mimicry." (PMID 33196458, 2020). "Some studies proposed the anti-angiogenic role of ANGPTL4 that it could prevent metastasis through inhibition of angiogenesis, tumor cell motility and invasion." (PMID 33196458, 2020). "HIF-1α-induced VEGF and ANGPTL4 expression can effectively promote tumor angiogenesis in melanoma." (PMID 32993787, 2020). "ANGPTL4 (Tumour cell-derived human angiopoietin-like protein 4) can damage vascular endothelial cell junctions, increase pulmonary capillary permeability, and promote the process of tumour cells protruding through the vascular endothelium." (PMID 32019546, 2020).
tumor (continued). "In addition, activation of PPAR‐γ induced the expression and secretion of ANGPTL4 in adipocyte lipid metabolism and tumor angiogenesis." (PMID 32638512, 2020). "Moreover, in a research on triple‐negative breast cancer (TNBC), heparin‐binding epidermal growth factor (HB‐EGF) was found to play a pivotal role in the acquisition of tumor aggressiveness by regulating both ANGPTL4 and VEGFA." (PMID 32410376, 2020). "Certain authors suggested that ANGPTL-4 prevents tumor metastasis by inhibiting vascular permeability, tumor cell motility, angiogenesis, and invasiveness; thus, ANGPTL-4 may have an antitumor effect, decreasing tumor growth and metastasis." (PMID 31741709, 2019). "In addition, epidermal growth factor receptor variant III (EGFRvIII) is able to induce ANGPTL4 expression through the ERK/c-Myc pathway and promotes tumor angiogenesis in malignant gliomas." (PMID 31717924, 2019). "The concentrations of ANGPTL-4 in plasma and tumor tissue were higher in the CC group." (PMID 31741709, 2019). "However, after being passaged in ACM, the expression of ANGPTL4 significantly increased in all tumor cells compared with CM control (p < 0.05 in MCF-7 and p < 0.005 in TNBC cells by the two-sided Student’s t-test)." (PMID 31602400, 2019). "Plasma and tumor levels of ANGPTL-4 were higher in CC in comparison to other groups." (PMID 31741709, 2019). "Accordingly, we suggest that the increase in plasma and tumor ANGPTL-4 levels in cancer cachexia patients may be partially responsible for the development of pre-cachexia and the progression to refractory cachexia." (PMID 31741709, 2019). "Interestingly, ANGPTL4 has been deemed a regulator of endogenous FN synthesis in tumor cells likely through an autocrine or paracrine manner." (PMID 31861892, 2019). "Conceptually, ANGPTL4 may alternatively induce endothelial retraction by promoting periFN assembly on CTCs that leads to an enhancement of tumor-endothelial adhesion via periFN-DPP IV binding." (PMID 31861892, 2019). "In addition, the expression of ANGPTL-4 is positively correlated to the increasing malignity of tumors, suggesting a role of ANGPTL-4 in tumor growth." (PMID 31741709, 2019). "Interestingly, ANGPTL4 is strongly related to angiogenesis and tumor migration via α5β1-integrin/RAC1 interaction." (PMID 31277479, 2019). "However, expression of the other hypoxia-specific genes: ERBB3 and CA9, ANGPTL4 was the highest at later stages of tumor development." (PMID 30412628, 2018). "Moreover, the tumor microenvironment influences the transcriptional regulation of ANGPTL4 in cancer." (PMID 29389861, 2018). "In addition, carbonic anhydrase 9 (CA9) and angiopoietin‐related protein 4 (ANGPTL4), proteins known to respond to tumor hypoxia, showed 13‐ and 3.6‐fold increases, respectively, in tumor tissue." (PMID 30459171, 2018). "In the early phases of the metastatic cascade, when the tumor cells are still outside the brain microenvironment, over-expression of ANGPTL4 in the cutaneous cells promoted characteristics that would enable their invasion to the target organ, the brain microenvironment." (PMID 29100268, 2017). "Furthermore, qRT-PCR and western blot assay also showed that the mRNA and protein levels of ANGPTL4 was higher in GCT samples than in para-tumor normal bone tissues." (PMID 28903395, 2017). "Moreover, knockout of ANGPTL4 by TALENs in GCTSCs inhibited tumor growth, angiogenesis and osteoclastogenesis in GCT in vitro." (PMID 28903395, 2017). "Also, the endothelial ANGPTL4 secretion induced by tumor-released semaphorin 4D (SEMA4D) has been shown to modulate vascular permeability." (PMID 28182091, 2017). "Moreover, tumour-derived ANGPTL4 interacts with integrins-β1 and -β5 to activate FAK, leading to the activation of Rac, which further activates the NADPH oxidase-dependent generation of O2−." (PMID 28894280, 2017).
tumor (continued). "Treatment with a specific ANGPTL4 inhibitor such as a neutralizing antibody may suppress tumour growth and peritoneal metastasis in patients with SGC." (PMID 28894280, 2017). "Furthermore both the secretion and proangiogenic activities of ANGPTL4 are highly dependent on the vGPCR expression by the Kaposi Sarcoma tumor microenvironment." (PMID 28182091, 2017). "Finally, all these studies suggested that both proangiogenic and antiangiogenic effects of ANGPTL4 are reliable and strongly dependent on the related tumor microenvironment." (PMID 28182091, 2017). "Indeed, ANGPTL4 mRNA has been found to be upregulated in the perinecrotic areas of different tumor types." (PMID 28182091, 2017). "A hypoxic environment may induce HIF-1α in the SGC tumour, and HIF-1α-induced ANGPTL4 may promote tumour growth by upregulation of c-Myc and downregulation of p27." (PMID 28894280, 2017). "Inhibition of ANGPTL4, which was highly expressed in hypoxic UM cells, a UM orthotopic transplant model, a UM tumor array, and vitreous samples from UM patients, inhibited the angiogenic potential of UM cells in vitro and in vivo; this effect was additive to VEGF inhibition." (PMID 26761211, 2016). "ANGPTL4 expression was detected in UM tumor cells in 78% of biopsies." (PMID 26761211, 2016). "The target gene ANGPTL4 is of particular interest in the context of the present study, since it not only figures in lipid metabolism as a regulator of lipoprotein lipase, but also plays an apparently essential role in tumor progression." (PMID 25968567, 2015). "ANGPTL4 has been reported as a tumor suppressor through inhibiting angiogenesis in gastric cancer." (PMID 26294325, 2015). "Moreover, elevated ANGPTL4 expression increased as tumours progressed from benign to metastatic states, thus implying a role of ANGPTL4 in tumour growth." (PMID 26508818, 2015). "Besides genes with metabolic functions, these include cell type-selective genes associated with immune regulation and tumor progression, e.g., LRP5, CD300A, MAP3K8 and ANGPTL4." (PMID 25968567, 2015). "ANGPTL4 also inhibits anoikis, which is essential for the survival of circulating tumor cells." (PMID 25968567, 2015). "ANGPTL4 has been identified in hypoxia gene sets that predict poor outcome in multiple tumor types." (PMID 25955030, 2015). "The exact function of ANGPTL4 in ovarian carcinogenesis is unclear; it may be that the function of ANGPTL4 is dependent on the level of transcript present and the tumour type it is expressed in." (PMID 26205780, 2015). "In contrast, hypoxia stimulates the expression of ANGPTL4 in several tumour types." (PMID 26508818, 2015). "Notably, NBCCS fibroblasts expressed higher mRNA levels of the anti-angiogenic protein ANGPTL4 which is known to limit tumor cell motility and invasiveness and the invasive potential of BCC cells, as well." (PMID 26694869, 2015). "ANGPTL4 mRNA is increased in the perinecrotic areas of many human tumours." (PMID 26508818, 2015). "First, overexpression of ANGPTL4 suppressed tumor growth through enhancing apoptosis of tumor cells, indicating that suppression of ANGPTL4 in HCC may be a way to escape from apoptosis." (PMID 25148701, 2014). "A study in HCC has showed that ANGPTL4 promotes tumor migration and metastases." (PMID 25148701, 2014). "However, many studies have suggested that ANGPTL4 can promote tumor growth, angiogenesis, invasion and metastasis." (PMID 25148701, 2014). "Treatment with Ad-ANGPTL4 significantly inhibited the in vivo tumor growth, invasiveness and metastasis by promoting tumoral apoptosis, inhibiting tumoral angiogenesis and motility, and suppressing tumor-favorable microenvironment." (PMID 25148701, 2014). "There have been several studies suggesting that ANGPTL4 is deregulated in cancers, whether it is elevated or suppressed in tumor is dependent on the types and the contexts of cancers." (PMID 25148701, 2014).
tumor (continued). "We evaluated the genes that encode vascular endothelial growth factor A (VEGFA, an isoform of VEGF that is crucial for tumor angiogenesis and plays a key role in endothelial cell proliferation, survival, and permeability), angiopoietin-like 4 (ANGPTL4), and carbonic anhydrase 9 (CA9)." (PMID 24918449, 2014). "HCC tissues expressed significantly lower levels of ANGPTL4 mRNA than non-tumor tissues." (PMID 25148701, 2014). "Our result demonstrated that patients with undifferentiated or poorly differentiated HCC had significantly lower levels of ANGPTL4 mRNA in tumor tissues, suggesting that deregulation of ANGPTL4 mRNA may indicate the status of tumor differentiation." (PMID 25148701, 2014). "We confirmed that ANGPTL4 upregulation plays important roles in ESCC development, and serum ANGPTL4 level may be a potential tumor marker for ESCC diagnosis and prognosis." (PMID 23925665, 2013). "Moreover, increase of Angptl4 expression in the mice bearing tumor xenografts of LN229-vIII was observed at both the mRNA and protein levels." (PMID 23617883, 2013). "In our study, whether the serum ANGPTL4 decrease after ESCC surgery is due to tumor load reduction, or its raised level in a certain period be related to tumor recurrence or progression should be validated by long-term follow-up data in the future." (PMID 23925665, 2013). "Moreover, ANGPTL4 has been reported to promote tumor growth, help tumor cells avoid anoikis, and facilitate tumor cell metastases by interfering with endothelial cell junctions and induction of vascular leakiness." (PMID 23925665, 2013). "In total, there were (delete) 52 cases (69.2 %) showed a higher level of ANGPTL4 protein expression in tumor tissues than that in normal tissues, with the average immunostaining scores in tumor tissues being 3.04 ± 1.80 and 1.42 ± 1.01 in normal tissues (P < 0.001)." (PMID 23925665, 2013). "There were 52 cases (69.2 %) showing a higher level of ANGPTL4 expression in tumor tissues than that in normal tissues, and the rate of ANGPTL4 protein high/moderate expression in ESCC and normal tissues was 55.1 % (43/78) and 6.4 % (5/78), respectively, with a significant difference (P < 0.001)." (PMID 23925665, 2013). "ANGPTL4 upregulation may play an important role in ESCC development, and serum ANGPTL4 level may be a potential tumor marker for ESCC diagnosis and prognosis." (PMID 23925665, 2013). "Wild-type EGFR expression, as compared to mock, increased tumor growth and Angptl4 expression in vivo, and also activated ERK phosphorylation in the LN229 cells; however, the degree of activation was not significantly different from that induced by EGFRvIII expression (data not shown)." (PMID 23617883, 2013). "In addition, tumor-secreted ANGPTL4 can disrupt the junction between adjacent endothelial cells by interacting with integrin α5β1 to activate the Rac/PAK signaling, followed by interaction with VE-cadherin and claudin-5." (PMID 22481923, 2012). "In addition to its effects on tumor cells, we investigated whether ANGPTL4 could impact the TME in TNBC." (PMID 39910592, 2025). "Furthermore, ANGPTL4 plays dual roles in both pro- and anti-angiogenesis, and is a secreted tumor suppressor that inhibits angiogenesis, and we speculate that ANGPTL4 may also play a role in inhibiting angiogenesis in propranolol therapy." (PMID 41487524, 2025). "Notably, cancer cell-driven paracrine signals appear to regulate ANGPTL4 expression in fibroblasts, suggesting that ANGPTL4 may act as a reciprocal factor in a feedback loop that enhances tumor progression." (PMID 39811640, 2025). "Moreover, plasma level of ANGPTL4 markedly declined after tumor resection in CRC patients." (PMID 38643448, 2024). "We next explored whether EC-specific deletion of Angptl4 promotes tumor FA uptake." (PMID 38086791, 2023).